ISL1 (ISL LIM homeobox 1)
Diseases named in the same sentence as ISL1 in open-access papers (continued):
Sharing a sentence is not in itself a finding about the gene and the disease.
diabetes (8 papers, 2011 to 2025). "STZ treatment also suppressed expression of a wide range of genes linked with key β-cell functions or diabetes development, such as G6pc2, Slc2a2 (Glut2), Slc30a8, Neurod1, Ucn3, Gad1, Isl1, Foxa2, Vdr, Pdx1, Fkbp1b and Abcc8, suggesting global β-cell defects in STZ-treated islets." (PMID 23828045, 2013). "In order to explore the biological functions of ISL1 in adult pancreatic islets, we detected the expression of ISL1 in different diabetes animal models." (PMID 21829621, 2011). "This activating STAT3 variant results in the decrease of insulin expression by repressing the transcriptional activity of ISL1, which could be involved in the pathogenesis of pancreatic β‐cell dysfunction and early‐onset diabetes." (PMID 38404237, 2024). "The inherited expression of Isl-1/Pax-6/Nkx6.1/Somatostatin transcripts in h-ASCs, its ease in availability and autologous origin, make it an eminent candidate for cell replacement therapy in diabetes." (PMID 21687731, 2011). "Moreover, regardless of diabetes status, nuclear ISL1 levels trended with nuclear NEUROD1 but were overall reduced in T1D, suggesting that, despite upregulation, a general impairment of nuclear access, potentially stemming from a reduction in importins, prevents α cell (re)maturation in T1D." (PMID 41026524, 2025).
neuroendocrine tumors (7 papers, 2019 to 2025). "As non-neuroendocrine tumors seldom express these antigens, the specificity of ISL1, INSM1 and SECG make them welcome additions to clinical practice." (PMID 34571751, 2021). "Nuclear staining of ISL1 was in concordance with previous studies that analysed the endocrine cells of pancreatic islets and neuroendocrine tumours." (PMID 32158343, 2020). "Subsequently, ISL1 expression has also been reported as a highly sensitive marker also for additional neuroendocrine neoplasms, such as Merkel cell carcinomas, pheochromocytomas, paragangliomas, and medullary thyroid carcinomas." (PMID 32813226, 2020). "Aberrant expression of ISL1 plays an important role in tumorigenesis, ISL1 serves as a biomarker of metastasis in pancreatic and extrapancreatic neuroendocrine neoplasms." (PMID 30674889, 2019). "The diagnostic arsenal has since expanded, with ISL LIM homeobox 1 (ISL1), INSM transcriptional repressor 1 (INSM1), and secretagogin (SECG) to name a few novel markers exhibiting high sensitivity and specificity for neuroendocrine neoplasms (NENs)." (PMID 32813226, 2020).
bladder cancer (5 papers, 2017 to 2024). "An increase in ISL1 promoter methylation is significantly associated with increased tumour number, size, grade and stage in bladder cancer." (PMID 32158343, 2020). "There was a study that identified a significant correlation between the methylation of ISL1 with increasing stage and grade of bladder cancer; suggesting that expression levels reduced as tumour progressed." (PMID 32158343, 2020). "In the bladder cancer dataset, ISL1 was selected as a hypomethylated biomarker." (PMID 38886487, 2024). "Vice versa we found dysregulation of ISL1 expression in three bladder cancers." (PMID 36352089, 2022). "In addition, ISL1 promoter methylation is frequently found in bladder cancer." (PMID 32158343, 2020). "The positive expression of ISL1 and LHX5 was detected in 94% and 98% of FFPE bladder cancer tissues, respectively." (PMID 37627900, 2023). "To date, there are still no studies done for ISL1 in advanced stages of bladder cancer tissue especially in bladder cancer that have metastasised." (PMID 32158343, 2020).
bladder exstrophy (5 papers, 2015 to 2024). Bladder exstrophy (or classic bladder exstrophy; CEB) is a congenital genitourinary malformation belonging to the spectrum of the exstrophy-epispadias complex (EEC) and is characterized by an evaginated bladder plate, epispadias and an anterior defect of the pelvis, pelvic floor and abdominal wall. "Using genome wide association methods, we identified ISL1 as the key susceptibility gene for classic bladder exstrophy (CBE), comprising epispadias and exstrophy of the urinary bladder." (PMID 39358471, 2024). "Mutations in the ISL1 gene were also significantly associated with bladder exstrophy in multiple meta-analyses, and ISL1 appears to impact genital tubercle development through downstream effects on Fgf10, Wnt5a, and Bmp4." (PMID 39594614, 2024). "At this point, ISL1 (ISL LIM homeobox 1) has emerged as the major susceptibility gene for classic bladder exstrophy (CBE), in a multifactorial disease model." (PMID 30563179, 2018). "Previously genome-wide association methods in patients with classic bladder exstrophy (CBE) found association with ISL1, a master control gene expressed in pericloacal mesenchyme." (PMID 28176844, 2017).
Hyperglycemia (5 papers, 2016 to 2023). An increased concentration of glucose in the blood. "Isl1CKO mice demonstrated a severe diabetic phenotype with significant neonatal hyperglycemia that worsened with age, consistent with earlier findings using delayed conditional deletion of Isl1 in Pdx1lateCre;Isl1f/f." (PMID 36899442, 2023). "Delayed conditional deletion of Isl1 in Pdx1lateCre;Isl1f/f during the secondary transition results in a severe hyperglycemia phenotype due to a significant reduction in insulin+, glucagon+, and somatostatin+ endocrine cells." (PMID 36899442, 2023). "PIASy and Isl1 mRNA expression levels were also increased in db/db mice with hyperglycaemia, which have been used as a type 2 diabetes model." (PMID 28000708, 2016).
type 2 diabetes (5 papers, 2011 to 2022). "Mutations in ISL1 were found to be associated with maturity-onset diabetes of the young and type 2 diabetes patients." (PMID 35970860, 2022). "The Isl1 mutation has been found to be associated with type 2 diabetes, but the mechanism responsible for Isl1 regulation of insulin synthesis and secretion still needs to be elucidated." (PMID 28000708, 2016). "Our results show that ISL1 expression was up-regulated at the mRNA level both in cultured pancreatic cells undergoing glucose oxidase stimulation as well in type 1 and type 2 diabetes mouse models." (PMID 21829621, 2011).
Arrhythmia (4 papers, 2013 to 2021). Any cardiac rhythm other than the normal sinus rhythm. "Islet1 (Isl1) is known to play a role in the development of the primary pacemaker, the SA node, as its deficiency causes cardiac arrhythmia." (PMID 34557935, 2021). "Moreover, in zebrafish, isl1 mutants showed bradycardia and arrhythmia phenotypes, implying a role of isl1 in cardiac conduction." (PMID 34901033, 2021). "Thus, it will be interesting to see if both SHOX2 and ISL1 are involved in human heart disease, especially arrhythmias." (PMID 23455426, 2013). "We hypothesize that selected clinical arrhythmias could be explained by a local diminished or absent down-regulation or re-expression of Isl1 resulting in areas with a more primitive, ‘CCS-like’ phenotype, from which arrhythmias originate." (PMID 25752780, 2015).
insulinoma (4 papers, 2014 to 2024). "The studies demonstrated that the identified GOF variants (p.Pro330Ser; p.Glu357Lys) led to hyper‐inhibition of ISL1 and consequently to a decrease in insulin gene expression in a rat insulinoma cell line." (PMID 38404237, 2024). "ISL1, also known as insulin gene enhancer binding protein 1, was first discovered in rat insulinoma cell line by Karlsson in 1990 and sequenced." (PMID 34131100, 2021).
congenital heart disease (3 papers, 2010 to 2019). "A replication study analyzed these candidate SNPs in 1,044 new cases and 3,934 independent controls and confirmed that genetic variation in ISL1 is associated with risk of non-syndromic congenital heart disease." (PMID 20520780, 2010). "Eight genic and flanking ISL1 SNPs were significantly associated with complex congenital heart disease." (PMID 20520780, 2010). "A 2-stage case-control study examined 27 polymorphisms mapping to the ISL1 locus in 300 patients with complex congenital heart disease and 2,201 healthy pediatric controls." (PMID 20520780, 2010). "The fundamental role of ISL1 in cardiac morphogenesis makes this an exceptional candidate gene to consider as a cause of complex congenital heart disease." (PMID 20520780, 2010). "Although mice deficient in Isl1 harbor defects in cardiac morphogenesis, the role of ISL1 in human congenital heart disease is unknown." (PMID 20520780, 2010). "ISL1 SNP associations with risk of congenital heart disease in US whites." (PMID 20520780, 2010). "Consistent with human studies which identified ISL1 variations and deletions contributing to congenital heart disease, all Isl1 hypomorphic mice (Isl1-f;neo/f;neo) died shortly after birth with severe cardiac malformations." (PMID 31024170, 2019). "While genetic variation in ISL1 is associated with congenital heart disease and cardiomyopathies, SHOX2 has not been linked to any human phenotype yet." (PMID 23455426, 2013).
lymphoma (3 papers, 2014 to 2020). A malignant (clonal) proliferation of B- lymphocytes or T- lymphocytes which involves the lymph nodes, bone marrow and/or extranodal sites. "Previously, we proved that ISL1 promoted the proliferation of adult pancreatic islet cells and lymphoma cells." (PMID 27183908, 2016). "To examine the pathological relevance of ISL-1 in human lymphoma development, we analyzed the expression level and cellular distribution of ISL-1 in collected specimens and tissue microarrays by immunohistochemical staining." (PMID 25070240, 2014). "The expression of ISL-1 was assessed in 211 human lymphoma samples and 23 normal lymph node samples." (PMID 25070240, 2014). "In parallel with the proportion of each NHL subtype, we performed immunohistochemical analyses for ISL-1 in 195 primary lymphoma tissue specimens, including 159 B-cell lymphoma and 36 T-cell lymphoma samples." (PMID 25070240, 2014). "These implied that c-Myc must be a more potent downstream factor of ISL-1 to mediate proliferation effects in lymphoma tumorigenesis." (PMID 25070240, 2014). "Collectively, in vitro and in vivo results indicate that overexpression of ISL-1 promotes NHL cells proliferation and enhances lymphoma development, whereas knockdown of ISL-1 attenuates NHL cells proliferation and inhibits xenograft growth." (PMID 25070240, 2014). "ISL-1 staining was predominantly detected in the nuclear of a series of NHL lymphoma cells and, to a much lesser extent, in the normal lymph nodes and HL samples." (PMID 25070240, 2014). "ISL1 also promotes the proliferation of non-hodgkin lymphoma cells in vitro." (PMID 32158343, 2020). "Interestingly, our data suggested that JNK and JAK/STAT pathways could corporately regulate c-Myc expression and promote lymphoma growth through up-regulating the level of ISL-1." (PMID 25070240, 2014). "The results showed that ISL-1 overexpression obviously promoted NHL cells proliferation, changed the cell cycle distribution in vitro and significantly enhanced xenografted lymphoma development in vivo." (PMID 25070240, 2014). "The results showed a high expression level of ISL-1 in diffuse large B cell lymphoma (DLBCL, the most common lymphoma subtype and accounting for 30 ~ 40% of adult non-Hodgkin lymphoma), compared with reactive lymph nodes (data not shown)." (PMID 25070240, 2014).
non-Hodgkin lymphoma (3 papers, 2014 to 2021). Distinct from Hodgkin lymphoma both morphologically and biologically, non-Hodgkin lymphoma (NHL) is characterized by the absence of Reed-Sternberg cells, can occur at any age, and usually presents as a localized or generalized lymphadenopathy associated with fever and weight loss. "Immunohistochemistry results demonstrated a markedly higher expression of ISL-1 in 75% of non-Hodgkin lymphoma (NHL) samples compared with that in normal lymph nodes or Hodgkin lymphoma (HL) samples." (PMID 25070240, 2014).
Obesity (3 papers, 2020 to 2025). Accumulation of substantial excess body fat. "The ISL1 missense variant found in our study segregated with the obesity phenotype in the family and was predicted disease causing." (PMID 32153512, 2020). "The role of ISL1 in the development of obesity and the functional relevance of the variant require further studies." (PMID 32153512, 2020). "High-fat diet (HFD)-induced obesity in mice reduces gene expression of Etv1, Isl1, Mlxipl, Nkx2.2 and Rfx6 whereas Cck, Gip and Pyy, Gcg gene expression is not impacted." (PMID 33037328, 2021). "Inactivation of Isl1 in Pomc neurons reduces the expression of Pomc and leads to obesity." (PMID 32153512, 2020). "Variants in ISL1 have previously been associated with congenital heart defects, but to our knowledge, no mutations in ISL1 have been reported in monogenic obesity." (PMID 32153512, 2020). "In addition, we identified rare heterozygous missense variants in ADCY3 (p.G1110R), MYT1L (p.R807Q), ISL1 (p.I347F), LRP2 (p.R2479I, and p.N3315S) and a hemizygous missense variant in GRPR (p.L87M) (each in one patient), possibly contributing to the obesity phenotype in these patients." (PMID 32153512, 2020).
pheochromocytoma (3 papers, 2021 to 2023). "In subsequent studies, ISL1 has been shown to also be expressed in pancreatic, duodenal, rectal and colonic NETs, in addition to Merkel cell carcinoma, pheochromocytoma/paraganglioma and medullary thyroid carcinoma." (PMID 34571751, 2021). "Immunoreactivity to classic neuroendocrine markers such as CgA and synaptophysin is almost always present, and second-generation neuroendocrine markers ISL LIM Homeobox 1 (ISL1) and INSM1 have also been found as reliable markers of an adrenal medullary origin in pheochromocytoma." (PMID 35205664, 2022). "Pheochromocytomas and abdominal paragangliomas stain positive for neuroendocrine markers CgA, SYP, ISL1, INSM1 and, often, GATA3; subsets of cases may display an intricate network of supporting sustentacular cells which are highlighted by an S100 or SOX10 stain." (PMID 37685605, 2023). "Similarly, pheochromocytomas and abdominal paragangliomas may be ISL1 and INSM1 positive, but are most often negative for SECG." (PMID 34571751, 2021).
prostate carcinoma (3 papers, 2019 to 2022). A carcinoma that arises from epithelial cells of the prostate gland. "Our findings reveal the important role of ISL1 in androgen receptor (AR)-dependent prostate cancer cell growth; ISL1 knockdown reduced the AR activity and cell growth." (PMID 34753990, 2021). "Elevated expression of ISL1 in some human cancers, including pancreatic and prostate cancers, suggesting that the function of ISL1 is tissue and context dependent." (PMID 30674889, 2019). "ISL1 is identified as a biomarker of oral squamous cell carcinoma, up-regulator of vascular development, and activator of EMT to induce drug resistance in prostate cancer, serving to regulate reproductive system development." (PMID 36504560, 2022).
retinal degeneration (3 papers, 2013 to 2025). Degeneration of the retina. "Since shh expression is expanded in Astyanax cavefish and shh mRNA leads to eye reduction when injected into developing surface fish, it is possible that mutations within isl1 could simultaneously contribute to both retinal degeneration and eye reduction." (PMID 23437360, 2013).
teratoma (3 papers, 2016 to 2023). A non-seminomatous germ cell tumor characterized by the presence of various tissues which correspond to the different germinal layers (endoderm, mesoderm, and ectoderm). "In this trial, the selected cells defined as cardiac progenitors (CD15+ Isl-1+), by definition lack maturation steps and the major focus for the investigator was to avoid injection of undifferentiated cells (to avoid teratoma formation)." (PMID 29043256, 2016). "Moreover, rare cases of renal NENs and NENs arising in teratomas included in our study were consistently positive for ISL1, which are novel findings worth exploring in larger materials." (PMID 32813226, 2020).
Anxiety (2 papers, 2021). Intense feelings of nervousness, tension, or panic often arise in response to interpersonal stresses. "A role for Abl2, Csmd2, Dlgap1, and Isl1 in neurodevelopment and psychiatric and neurodegenerative diseases have been reported in previous studies and our association analysis suggests a role in anxiety." (PMID 33431988, 2021). "Several anxiety-associated genes had direct interactions with striatal development genes, such as PRKCA with ADCY5 and DLX3, and ESR1 with ISL1." (PMID 34526518, 2021).
atrial septal defect (2 papers, 2018 to 2019). Interauricular communication is a congenital malformation characterized by a communication between the atrial chambers of the heart. "Nearly all Isl1 hypomorphic mice presented ventricular septal defects (VSDs) and atrial septal defects (ASDs)." (PMID 31024170, 2019). "The DMP, which represents the protrusion of discrete mesenchymal cells from the DM toward the atrial cavity, is derived from the Isl1-expressing SHF lineage and is associated with atrioventricular septal defects." (PMID 29367466, 2018).
autism (2 papers, 2014 to 2020). Persistent deficits in social interaction and communication and interaction as well as a markedly restricted repertoire of activity and interest as well as repetitive patterns of behavior. "Another candidate gene for autism, ISL1 (ISL LIM homeobox 1), significantly upregulated in our RSTS neurons, was found downregulated in individuals with duplications of chromosome 15q11-q13.1, which account for 1 to 3% of all autism cases." (PMID 32562237, 2020).
embryonic carcinoma (2 papers, 2013 to 2017). "To further test whether Gaa, Isl1, Kif1b, Mtmr2, Pcsk1n, and Snca, are regulated by Pax6, we performed co-transfection studies in cultured P19 embryonic carcinoma and αTN4-1 lens epithelial cells." (PMID 23342162, 2013). "To test whether the Isl1-Lhx3 complex directly activates transcription via Lhx3-Peak-A, even without initiating MN fate specification, we performed luciferase reporter assays in cultured mouse embryonic carcinoma P19 cells." (PMID 28451636, 2017).
Insulin resistance (2 papers, 2019 to 2020). Increased resistance towards insulin, that is, diminished effectiveness of insulin in reducing blood glucose levels. "A single-nucleotide polymorphism (SNP) in ISL1 elevates body weight in NIDDM patents with insulin resistance." (PMID 30678306, 2019). "On the other hand, the Wnt signaling pathway is also related to the development of some DRD2s, for example, miR-128-3p aggravates cardiovascular calcification and insulin resistance in T2D rats by downregulating ISL1 through the activation of the Wnt pathway." (PMID 33381155, 2020).
ischemia (2 papers, 2012 to 2020). A hypoperfusion of the BLOOD through an organ or tissue caused by a PATHOLOGIC CONSTRICTION or obstruction of its BLOOD VESSELS, or an absence of BLOOD CIRCULATION. "The protein expression levels determined by Western blot correlated consistently with the mRNA data, with the highest protein expression of c-Kit, Isl1 and Nkx2.5 in the ischemia-reperfusion injury groups (IR and IR+GF)." (PMID 22590612, 2012).
Merkel cell carcinoma (2 papers, 2023 to 2025). "Here, we show that MCPyV+ Merkel cell carcinoma is defined by neuroendocrine-lineage core regulatory (CR) transcription factors (TFs) (ATOH1, INSM1, ISL1, LHX3, POU4F3, and SOX2) that were essential for tumor survival and that co-bound chromatin with the viral small T antigen at super enhancers." (PMID 41392987, 2025).
Myocardial fibrosis (2 papers, 2015 to 2018). "Intramyocardial gene transfer of ISL1 to the border zone of infarcted hearts results in partial salvage of left ventricular function, enhanced vascularization, and reduced myocardial fibrosis." (PMID 29482621, 2018). "CSCs expressing Isl1 exhibited increased angiogenic gene expression and interestingly intramyocardial delivery of isl1 gene markedly accelerated the functional recovery and reduced myocardial fibrosis in mice subjected to MI." (PMID 25802528, 2015).